ZBTB38 (zinc finger and BTB domain containing 38)
Description:
Transcriptional regulator with bimodal DNA-binding specificity. Binds with a higher affinity to methylated CpG dinucleotides in the consensus sequence 5'-CGCG-3' but can also bind to E-box elements (5'-CACGTG-3'). Can also bind specifically to a single methyl-CpG pair. Represses transcription in a methyl-CpG-dependent manner. Plays an important role in regulating DNA replication and common fragile sites (CFS) stability in a RBBP6- and MCM10-dependent manner; represses expression of MCM10 which plays an important role in DNA-replication. Acts as a transcriptional activator. May be involved in the differentiation and/or survival of late postmitotic neurons (By similarity).
Synonyms: FLJ35036; CIBZ; ZNF921; PPP1R171
Tractability: PROTAC: UniProt records ubiquitination sites on it; ubiquitination databases record sites on it.
Gene: Protein-coding gene on chromosome 3 (141,324,154 to 141,449,792, forward strand). Ensembl gene ENSG00000177311.
Subcellular location: Nucleus; Chromosome
Subcellular location (Human Protein Atlas): Nucleoplasm
Gene Ontology:
Molecular function: methyl-CpG binding; protein binding; protein homodimerization activity; DNA-binding transcription factor activity; DNA-binding transcription factor activity, RNA polymerase II-specific; RNA polymerase II cis-regulatory region sequence-specific DNA binding
Biological process: DNA damage response; negative regulation of DNA-templated transcription; regulation of DNA replication; positive regulation of transcription by RNA polymerase II; regulation of DNA-templated transcription
Cellular component: blood microparticle; chromosome; nucleoplasm; nucleus
Genetic constraint (gnomAD): Loss-of-function variants: 23 observed, 83.72 expected, observed/expected ratio (o/e) 0.27, 90% interval 0.2 to 0.39. The upper end of that interval is the gene's LOEUF score, 0.39, which puts it in group 1 of 6, group 1 being the genes least tolerant of losing a copy. Missense variants: 1,082 observed, 1,561.5 expected, observed/expected ratio (o/e) 0.69, 90% interval 0.66 to 0.73. Synonymous variants: 504 observed, 575.78 expected, observed/expected ratio (o/e) 0.88, 90% interval 0.81 to 0.94.
Homologues: Orthologues: chimpanzee ZBTB38 (99% identical), macaque ZBTB38 (99% identical), guinea pig ZBTB38 (91% identical), dog ZBTB38 (89% identical), pig ZBTB38 (88% identical), rabbit ZBTB38 (85% identical), mouse Zbtb38 (81% identical), rat Zbtb38 (81% identical), tropical clawed frog zbtb38 (44% identical), Caenorhabditis elegans spr-3 (9% identical), Caenorhabditis elegans unc-98 (5% identical), Caenorhabditis elegans T22C8.3 (4% identical), and 1 more. Paralogues in human: ZBTB4 (21% identical), ZNF438 (10% identical).
Diseases named in the same sentence as ZBTB38 in open-access papers:
ZBTB38 is named in the same sentence as 42 diseases in open-access papers, as found by Europe PMC text mining. Sharing a sentence is not in itself a finding about the gene and the disease. The quoted sentences say what the papers report.
prostate carcinoma (12 papers, 2012 to 2025). A carcinoma that arises from epithelial cells of the prostate gland. "Our study for the first time determined the role of PRKDC as an interacting protein associated with the tumor suppressor ZBTB38 to promote DKK1 expression in prostate cancer." (PMID 34697293, 2021). "Previous large-scale GWAS studies found that rs6763931, an SNP site located in ZBTB38 gene region, is a prostate cancer risk SNP, which indicated the potential role of ZBTB38 in prostate cancer." (PMID 34697293, 2021). "We explored the DEGs that were both directly bound by ZBTB38 and reported to be implicated in prostate cancer disease progression." (PMID 34697293, 2021). "The depletion of ZBTB38 thus causes heightened levels of ROS within prostate cancer cells, as observed in other cancer cell types." (PMID 32365491, 2020). "Analysis of different prostate cancer cohorts indicates that low expression levels of ZBTB38 associate with increased levels of chromosomal abnormalities and more aggressive pathological features, including higher rate of biochemical recurrence of the disease." (PMID 32365491, 2020). "Low expression levels of ZBTB38 (below median value) associates with higher prostate cancer recurrence in the TCGA and Taylor cohorts when all patients are considered in the analysis." (PMID 32365491, 2020). "We investigated the association between ZBTB38 expression levels and clinico-pathological features in prostate cancer patients." (PMID 32365491, 2020). "In here, we unveil a strong association between ZBTB38 and several clinico-pathological and genomic features of prostate cancer, including a strong association with SPOP and SPOPL alterations." (PMID 32365491, 2020). "Genetic analyses have shown that a polymorphism linked with ZBTB38 mRNA expression is associated with increased risk of prostate cancer." (PMID 32365491, 2020). "Our results indicate a strong association between low ZBTB38 expression in localised tumours with heightened levels of chromosomal instability as well as mutations of SPOP, which reinforce the association of ZBTB38 with aggressive prostate cancer." (PMID 32365491, 2020). "Results from a genome-wide association study (GWAS) done on prostate cancer patients revealed that polymorphisms in ZBTB38 gene increase the risk of developing prostate cancer in men." (PMID 31245293, 2019). "Down-regulation of ZBTB38, a novel substrate of caspase-3, induces apoptosis and this gene is localized in a prostate cancer susceptibility locus." (PMID 22952676, 2012). "Recently, a SNP in intron 4 of ZBTB38 was associated with prostate cancer risk in a multistage genome-wide association study, further supporting this hypothesis." (PMID 24700353, 2014). "Interestingly, it was shown that ZBTB38 expression is associated to ROS signalling in cancer cells, suggesting a role of ZBTB38 in the regulation of ROS levels and doxorubicin sensitivity in prostate cancer." (PMID 32365491, 2020). "In bladder cancer, ZBTB38 promotes migration and invasive growth, while in prostate cancer, depletion of ZBTB38 results in higher expression of ROS and elevated cell death after doxorubicin treatment." (PMID 35410350, 2022). "In prostate cancer ZBTB38 expression is lower in tumors compared with benign prostatic hypertrophic and normal tissue, and lower expression is associated with higher pathological grade and poorer outcome." (PMID 35178492, 2022). "Although previous research has revealed the tumor-suppressive role of ZBTB38 in prostate cancer, however, the mechanisms are still unclear." (PMID 34697293, 2021). "We find lower ZBTB38 expression in prostate cancer tissues, which also strongly predicts a poorer prognosis of prostate cancer." (PMID 34697293, 2021). "Taken together, these findings uncovered the tumor-suppressive roles of ZBTB38 to suppress cell proliferation and migration in prostate cancer cells." (PMID 34697293, 2021).
prostate carcinoma (continued). "In this study, we studied the function and mechanism of ZBTB38 in the progression of prostate cancer systematically." (PMID 34697293, 2021). "We found that ZBTB38 expresses much lower in prostate cancer tissues, and its expression is reversely correlated with prostate cancer disease progression." (PMID 34697293, 2021). "To confirm the results from online data sets, we examined the expression of ZBTB38 by immunohistochemistry (IHC) in prostate cancer tissues." (PMID 34697293, 2021). "To explore the function of ZBTB38 in prostate cancer, we first determined the expression level of ZBTB38 in benign and cancer tissues." (PMID 34697293, 2021). "Microarray-based expression analyses using GSE35988 and GSE21032 data sets indicated significantly reduced ZBTB38 expression in primary and metastatic prostate cancer samples." (PMID 34697293, 2021). "Our results above showed the lower expression level of ZBTB38 in prostate cancer and suggested the potentially important role of ZBTB38 in disease progression." (PMID 34697293, 2021). "Our results indicated the tumor-suppressing role of ZBTB38 in both AR-positive prostate cancer and CRPC cells." (PMID 34697293, 2021). "To further determine the role of ZBTB38 in prostate cancer progression, we overexpressed ZBTB38 in LNCaP, DU145, and PC-3 prostate cancer cell lines." (PMID 34697293, 2021). "Consistently, reduction of DKK1 expression significantly restores ZBTB38-mediated suppression of migration and proliferation of prostate cancer cell lines." (PMID 34697293, 2021). "To study ZBTB38 significance in prostate cancer, we exploited publicly available data from several published prostate cancer study cohorts that have both comprehensive molecular and clinico-pathological data." (PMID 32365491, 2020). "In this cohort, ZBTB38 expression is also significantly lower in prostate cancer compared to normal prostate tissues." (PMID 32365491, 2020). "Future studies, including additional patients, may yield more robust information regarding ZBTB38 mRNA association with prostate cancer aggressiveness, particularly in different ethnic populations or for patients with intermediate-risk (i.e., Gleason 7) prostate cancer." (PMID 32365491, 2020). "In the present study, we exploited 10 publicly available and well-annotated datasets (including gene expression, genomic information and clinico-pathological data) to unravel a function of ZBTB38 in prostate cancer." (PMID 32365491, 2020). "The differential expression of ZBTB38 between control and prostate cancer specimens was computed separately for each cohort." (PMID 32365491, 2020). "We next investigated the prognostic value of ZBTB38 expression in prostate cancer patients using biochemical recurrence after primary curative treatment as a readout of disease-free survival." (PMID 32365491, 2020). "Here, we tested the clinical significance of ZBTB38 expression in prostate cancer, based on the analysis of publicly available and freely re-usable large-scale genomic and clinical datasets." (PMID 32365491, 2020). "Consistently, we demonstrated that depletion of ZBTB38 in prostate cancer cell lines leads to increase levels of ROS within cells and increase cell death upon doxorubicin treatment." (PMID 32365491, 2020). "Genome-wide association studies (GWAS) have identified a single-nucleotide polymorphism in the gene ZBTB38 (Zinc finger and BTB-domain containing protein 38), linked to the risk for men to develop prostate cancer." (PMID 32365491, 2020). "We further explored the role of ZBTB38 in prostate cancer by transfecting siRNA to knock-down ZBTB38 expression in prostate cancer cell lines, representative of different cancerous and hormonal status." (PMID 32365491, 2020). "Moreover, we found that ZBTB38 downregulation was also related to the progression and prognosis of prostate cancer." (PMID 34697293, 2021).
prostate carcinoma (continued). "We found that overexpression of ZBTB38 could repress the proliferation and migration of prostate cancer cells, and its expression is reversely correlated with prostate cancer disease progression." (PMID 34697293, 2021). "Moreover, only one previous research last year showed the preliminary study on the role of ZBTB38 in the initiation and progression of prostate cancer." (PMID 34697293, 2021). "However, the roles and mechanisms of ZBTB38 in prostate cancer are still unclear and need further research." (PMID 34697293, 2021). "Overexpression of ZBTB38 could repress the proliferation and migration of prostate cancer cells via direct promotion of DKK1 expression." (PMID 34697293, 2021). "Our results suggest the novel role of DKK1 in prostate cancer, which could serve as the direct downstream of ZBTB38 in regulating prostate cancer cells proliferation and migration." (PMID 34697293, 2021). "It is possible that ZBTB38 also contributes to the development of advanced prostate cancer." (PMID 34697293, 2021). "To further validate that DKK1 could mediate the tumor suppressor role of ZBTB38 in prostate cancer cells, we then knocked down DKK1 expression in DU145 cells." (PMID 34697293, 2021). "Here in this study, we show that tumor suppressor ZBTB38 could suppress the migration and proliferation of prostate cancer cells." (PMID 34697293, 2021). "We also identified that PRKDC could interact with ZBTB38 and regulate its tumor-suppressive roles in prostate cancer." (PMID 34697293, 2021). "Then we did transwell assays to explore the role of ZBTB38 in prostate cancer cell migration." (PMID 34697293, 2021). "Here in this study, we focused on ZBTB38 and investigated its role in prostate cancer progression." (PMID 34697293, 2021). "Taken together, our results indicate that ZBTB38 could repress cell migration and proliferation in prostate cancer via promoting DKK1 expression, and also provide evidence supporting ZBTB38 as a potential prognosis marker for prostate cancer." (PMID 34697293, 2021). "Results showed that overexpression of ZBTB38 could significantly inhibit prostate cancer cell proliferation." (PMID 34697293, 2021). "In our study, we make an investigation that ZBTB38 could interact with PRKDC to promote DKK1 expression to suppress prostate cancer cell proliferation and migration." (PMID 34697293, 2021). "To explore a possible mechanism linking ZBTB38 low expression with prostate cancer aggressiveness, we investigated whether ZBTB38 expression levels were associated with specific molecular features of prostate cancer." (PMID 32365491, 2020). "ZBTB38 paralogs, ZBTB4 and ZBTB33/KAISO, are also implicated in the progression of prostate cancer." (PMID 32365491, 2020). "Our study shows that ZBTB38 is involved in prostate cancer pathogenesis and may represent a useful marker to identify high risk and highly rearranged localised prostate cancer susceptible to doxorubicin." (PMID 32365491, 2020). "ZBTB38 is thus involved in the regulation of ROS levels in prostate cancer cells, which may favour genomic instability and carcinogenesis, as well as provide avenues for doxorubicin treatments." (PMID 32365491, 2020). "We further observed that ZBTB38 mRNA expression is an independent marker of DFS in prostate cancer." (PMID 32365491, 2020). "Using these different cohorts, we addressed whether ZBTB38 expression levels would be correlated with disease-free survival in prostate cancer patients." (PMID 32365491, 2020). "This suggest that monitoring ZBTB38 mRNA levels might help in the detection of patients with poor prognosis prostate cancer." (PMID 32365491, 2020). "This hypothesis remains to be tested but it grants further investigation of ZBTB38 as a molecular driver of prostate cancer progression, in relation to SPOP/SPOPL functions." (PMID 32365491, 2020).
prostate carcinoma (continued). "Low ZBTB38 expression is associated with worse prognosis in prostate cancer; again, the molecular links are not fully elucidated but may involve the function of ZBTB38 in regulating DNA replication or oxidative stress." (PMID 35625988, 2022). "However, prevalence of ZBTB38 expression in prostate cancer remains to be properly documented." (PMID 32365491, 2020). "ZBTB38 binds DKK1 (Dickkopf WNT signaling pathway inhibitor 1) locus and promotes DKK1 expression in prostate cancer cell lines." (PMID 34697293, 2021). "Although ZBTB38 has not been previously investigated in GC, it has been characterized as a tumor suppressor in prostate cancer and conversely, as an oncogene in bladder cancer." (PMID 40567896, 2025). "Then we investigated the correlation between ZBTB38 and DDK1 expression in prostate cancer samples." (PMID 34697293, 2021). "ZBTB38 mRNA levels is thus consistently lower in prostate cancer compare to non-cancerous prostate tissue." (PMID 32365491, 2020). "Depletion of ZBTB38 in prostate cancer cell lines, however, did not alter cell proliferation." (PMID 35178492, 2022). "RT-qPCR analysis show that ADAM10, ARMC8, COMMD8, EEA1 and PPM1B were expressed at similar levels in prostate cancer cells transfected with ZBTB38 and control siRNAs suggesting that these genes are not regulated by ZBTB38, but rather co-regulated by a common upstream factor and/or pathway." (PMID 32365491, 2020).
bladder cancer (5 papers, 2019 to 2025). "Zinc finger and BTB domain-containing 38 (ZBTB38) has been reported to promote EMT in bladder cancer cells by activating Wnt/β-Catenin signaling pathway." (PMID 34708244, 2022). "In bladder cancer, ZBTB38 promotes migration and invasive growth via modulation of the Wnt/β-catenin signalling pathway." (PMID 32365491, 2020). "In bladder cancer cells, ZBTB38 promotes cell migration and invasion, in part, by regulating Wnt/β-catenin signalling." (PMID 32365491, 2020). "In bladder cancer cells, ZBTB38 increased cell migration, invasion, and metastasis via regulating genes belonging to the Wnt/β-catenin signaling pathway but decreased bladder cancer cell proliferation." (PMID 31245293, 2019).
neuroblastoma (4 papers, 2017 to 2020). Neuroblastoma (NB) is the most common solid, extracranial childhood tumor. "We show here that Zbtb38 is downregulated under endoplasmic reticulum (ER) stress, which promotes ER stress-associated apoptosis in human bone marrow neuroblastoma cells." (PMID 28514761, 2017). "As a transcription factor, ZBTB38 is involved in cell regulation, proliferation and apoptosis, whereas, functional deficiency of ZBTB38 induces the human neuroblastoma (NB) cell death potentially." (PMID 30697495, 2019). "In neuroblastoma cell lines, depletion of ZBTB38 affects the expression of key cancer pathways including tyrosine receptor kinase signalling, cell cycle and checkpoint genes as well as autophagy-related genes." (PMID 32365491, 2020). "In contrast, ZBTB38 expression has been shown to promote proliferation and differentiation of a neuroblastoma cell line." (PMID 32956421, 2020). "ER stress blocked the transcription factor ATF4 to bind to the Zbtb38 gene promoter, which in turn inhibited Zbtb38 expression to trigger apoptosis in human bone marrow neuroblastoma cells and injured mouse spinal cord." (PMID 28514761, 2017). "To study whether ER stress affects Zbtb38 expression, we treated human bone marrow neuroblastoma cells SH-SY5Y with 1 μM thapsigargin (TG) and determined Zbtb38 expression by quantitative RT-PCR (QRT-PCR)." (PMID 28514761, 2017).
myopia (3 papers, 2013 to 2024). "In the genetic analysis of myopia control, it was discovered that ZBTB38 has an impact on the conjunctival area." (PMID 39295864, 2024).
Obesity (2 papers, 2020 to 2023). Accumulation of substantial excess body fat. "In Open Targets Genetics, genes near the ZBTB38, UBAP2 and ZNF236 loci show associations with various cancers, diabetes and obesity (no relevant mouse data available for these genes)." (PMID 33290408, 2020).
asthma (1 paper, 2018). "In an autoimmune disease analysis, PheWAS reported an association between enhancer SNP rs6763931 (located in an intron of ZBTB38) and asthma." (PMID 29378629, 2018).
breast carcinoma (1 paper, 2021). "By contrast, when using this threshold, ZBTB38 had only 3 negative and 1 positive correlations with gene regions in NSCLC and only 1 negative correlation in breast cancer cell lines." (PMID 33676569, 2021).
Cirrhosis (1 paper, 2024). A chronic disorder of the liver in which liver tissue becomes scarred and is partially replaced by regenerative nodules and fibrotic tissue resulting in loss of liver function. "Changes in the methylation and transcriptional levels of ZBTB38, ZC3H3, FOXK1, and KAZN are important for the development of fibrosis and HCC; and are therefore potential therapeutic targets and diagnostic tools for cirrhosis and HCC." (PMID 38302914, 2024).